STAT3 (signal transducer and activator of transcription 3)
Diseases named in the same sentence as STAT3 in open-access papers (continued):
Sharing a sentence is not in itself a finding about the gene and the disease.
tumor (continued). "Follow-up in vitro studies revealed an anti-inflammatory and pro-tumour effect of STAT3 ASO mediated by PSCs and MDSCs distinct from ablation of STAT3." (PMID 39886125, 2024). "Tumor-derived GM-CSF can activate neutrophils and induce PD-L1 expression via the JAK/STAT3 signaling pathway." (PMID 39877377, 2024). "The results of Western blot and IHC demonstrated that the expressions of p‐STAT3 and HK2 were promoted in tumor from nude mice with NSD3‐knockout PC9 cells." (PMID 39119928, 2024). "Overexpression of inflammatory factors promotes tumor development, while targeting inflammatory mediators, such as chemokines, cytokines (TNF-α and IL-1β), and key transcription factors (NF-κB and STAT3), reduces cancer growth and spread." (PMID 38502348, 2024). "Overexpression of MUC16 in lung cancer enhances tumor growth and migration, while also influencing development and metastasis through the JAK2/STAT3/GR axis, potentially contributing to chemotherapy resistance to agents like cisplatin and gemcitabine." (PMID 38361923, 2024). "Similar to STAT3 and C/EBPβ, TAZ activity promotes GBM tumor necrosis, which also propagates MES reprogramming and stemness." (PMID 38891074, 2024). "Alternately activated (M2) macrophages promote tumor growth and invasiveness in HCC, and stimulate HCC cell migration and epithelial-mesenchymal transition through the TLR4/STAT3 signaling pathway." (PMID 38318171, 2024). "In the context of cancer, ANXA1 has been shown to be involved in STAT3, PI3K and MAPK/ERK signalling pathways which promote tumour initiation and progression." (PMID 38200229, 2024). "The nanocomplex LP-R/C@AC killed tumor cells effectively in vitro by inducing apoptosis, autophagy, and pyroptosis while inhibiting tumor invasion and metastasis significantly through the VEGFR2/STAT3 pathway." (PMID 39409942, 2024). "Resveratrol has demonstrated the ability to inhibit tumor growth and enhance the sensitivity of cancer cells to chemotherapy by targeting the JAK-STAT signaling pathway, particularly through STAT3 downregulation." (PMID 39769099, 2024). "Together these data indicate that STAT3 is a genetic modifier that can regulate KRAS dependency and tumor development through counterposing EMT." (PMID 38573819, 2024). "M1-like macrophages can counteract HCC progression by modulating the tumor microenvironment, whereas M2-like macrophages can promote HCC cell proliferation and invasion by activating the TLR4/STAT3 signaling pathway." (PMID 39091612, 2024). "Further treatment with cordycepin in a mouse tumor model revealed reduced expression of Ki-67, p-EGFR, and p-STAT3 in cancer tissues." (PMID 39690423, 2024). "In neuroblastoma cell assays, copper chelators inhibit STAT3 phosphorylation, promote ubiquitin‐mediated degradation of PD‐L1, increase the number of infiltrated CD8+ T cells and slow tumour growth." (PMID 38801402, 2024). "Within tumour-infiltrating lymphocytes there was expansion of CD4 and PD-1+ CD8 populations with STAT3 ASO." (PMID 39886125, 2024). "The upregulation of STAT3, a transcription factor known for its role in cell survival and immune evasion, along with HIF1A facilitates a cellular environment conducive to tumor growth and immune system suppression." (PMID 39468431, 2024). "F. nucleatum invades intestinal epithelial cells and binds to DHX15, a protein of RNA helicase family expressed on CRC tumor cells, mechanistically involving ERK/STAT3 signaling." (PMID 38402201, 2024). "STAT3 sustains the KRAS-dependent phenotype and tumor aggressiveness, with the potential for improved efficacy of anti-RAS drugs, whereas SMAD4 promotes KRAS independence at the expense of enhanced therapy resistance." (PMID 38573819, 2024).
tumor (continued). "Our analysis also revealed an enrichment of IL-6/JAK/STAT3 signaling in CD8+ T cells, which is known to enhance proliferation, survival, invasiveness, and metastasis of tumor cells." (PMID 38169544, 2024). "Western blot analysis of tumor lysates harvested on day 26 confirmed that αEGFR-E-P125A–treated tumors demonstrated decreased phosphorylation of EGFR at Y1069, FAK at Y397, and STAT3 at Y705 compared with controls." (PMID 38315147, 2024). "Another discovery showed that by activating STAT3, the master factor of mesenchymal transition, OPN encourages the growth of myeloid-derived suppressor cells (MDSCs) and suppresses anti-tumor immunity." (PMID 37692522, 2024). "Conversely, breast cancer cells produce IL-6, which activates the JAK2/STAT3 axis, inducing TAMs to secrete TGF-β1, thereby forming a positive feedback loop that ultimately facilitates malignant tumor progression." (PMID 38965216, 2024). "Previous studies reported that HHT exerts anti-tumor effects by regulating several signaling pathways, including the MEK/ERK, PI3K/AKT, and JAK2/STAT3 signaling pathway." (PMID 38770133, 2024). "Immunohistochemical analysis of the in situ tumors revealed concurrent elevation of p-STAT3 and the vascular marker CD31, as well as the proliferation marker Ki67, promoting tumor metastasis to the lungs." (PMID 38920657, 2024). "Other cytokines, such as IL-17A, TNF-α, and IL-6, activate NF-kappa β and signal transducer and activator of transcription 3 (STAT3), inducing tumor growth." (PMID 39456655, 2024). "The upregulation of S1PR1 can activate STAT3, which binds to the promoter of S1PR1 to regulate its transcription, forming a positive feedback loop and accelerating tumor growth and metastasis." (PMID 38163890, 2024). "Lycorine and lycorine hydrochloride demonstrated anticancer effects through the regulation of multiple signaling pathways in tumor cells, including mTOR, NF-κB, JNK/STAT3, and ERK, among others." (PMID 39245716, 2024). "Induction of tumor cells stimulates osteoclasts to secrete the IL-20RB ligand IL-19, which activates JAK1/STAT3 signaling and thus promotes proliferation of bone metastatic cancer cells." (PMID 38464516, 2024). "The combined influence of the Th17/STAT3 axis and TRM cell activity in predicting ICI response underscores the complexity of these pathways and suggests that their roles in tumor immunity and therapy response warrants further investigation." (PMID 39514276, 2024). "STAT3 regulates PLG expression, promoting a thrombotic state that facilitates tumor cell migration and invasion in ccRCC." (PMID 39348357, 2024). "Research has shown that celastrol inhibits STAT3 by suppressing the activation of upstream kinases c-Src and Janus-activated kinases -1 and -2 (JNK 1/2), impacting tumor cell proliferation." (PMID 39494324, 2024). "CAFs have been shown to support tumor cells through exosomal transfer and the paracrine signaling mediated by NF-κB and cytokines such as IL-6, thereby activating the downstream JAK/STAT3, mechanistic target of rapamycin (mTOR), and SHH pathways." (PMID 38318525, 2024). "Abnormal expression of MUC16 promotes tumor progression through mesenchymal protein, PI3K/AKT pathway, JAK2/STAT3 pathway, ERK/FBW7/c-Myc, and other mechanisms, and plays an important role in the occurrence and development of tumors." (PMID 38758220, 2024). "MiR-24-1-5p expression was negatively correlated with tumor-related immune suppression pathways such as the IL2/STAT5 and IL6/JAK/STAT3 signaling pathways." (PMID 38840234, 2024). "It mediates activation of the JAK/STAT3, Ras/MAPK, and PI3K/AKT signaling pathways, promoting tumor development." (PMID 38831470, 2024). "In terms of tumor proliferation, the HMGB1/RAGE axis promotes tumor cell growth through several signaling pathways, including NF-kB, K-Ras, MAPK, AKT, mTOR, STAT3, MEK, and ERK1/2." (PMID 38529373, 2024).
tumor (continued). "Some STAT3 inhibitors, such as napabucasin and BBI608, have been proven to suppresse tumour progression and enhance antitumour effects in human and mouse models." (PMID 37950040, 2024). "Co-targeting IGF-1R and STAT3 can inhibit tumor metastasis and overcome resistance to anti-IGF-1R therapy by preventing pro-angiogenic cytokine production and tumor angiogenesis." (PMID 39273251, 2024). "Employing mouse tumor models could serve as a next step to verify the effectiveness of therapeutic interventions Future research, especially those utilizing multispecies disease models, is poised to substantially enhance our comprehension of STAT3's pivotal role in ESCC." (PMID 39468431, 2024). "YTHDF1 recognizes m6A modification of JAK1 mRNA in Tumor-infiltrating myeloid cells mediated by METTL3, and METTL3-m6A-YTHDF1 enhances the translation of JAK1 mRNA, subsequently promoting STAT3 phosphorylation and tumor growth in mice." (PMID 39726589, 2024). "The anticancer mechanisms of sorafenib and 5-MTP have been demonstrated to target the same molecule, the signal transducer and activator of transcription 3 (STAT3), which plays a crucial role in tumor cell proliferation and survival." (PMID 38388902, 2024). "Previous research has also reported that miR-452, a tumor suppressor miRNA, regulates the JAK1/STAT3 pathway in inflammatory colitis and CRC through IL20RA." (PMID 38185635, 2024). "As major components in the regulation of cytokine induced survival and proliferation, STAT3 and STAT5 play an important function in tumor growth and survival through the regulation of metabolic processes, such as glycolysis and oxidative phosphorylation." (PMID 38464736, 2024). "By activating EGFR and coupling with intercellular signaling proteins, numerous tumor-related signaling pathways, such as RAS, AKT, and STAT3, are involved in tumor progression." (PMID 38831321, 2024). "In tumor samples, the expression of IDH2, HIF1b, HIF2a, EGRF, PTEN and STAT3 was significantly downregulated, but HIF1a and VEGFC expressions were upregulated in U87MG STAT3 KO variant in comparison with U87MG cells." (PMID 38654280, 2024). "In vitro, RSV can exert anti-tumor effects on GBM and improve the inflammatory response in the GBM microenvironment by inhibiting the activation of the JAK2/STAT3 signaling pathway." (PMID 38546908, 2024). "IL-6/signal transducer and activator of transcription 3 (STAT3) signaling pathway was analyzed using qRT-PCR and Western blot in PC3 and DU145 cells and xenograft tumor tissues." (PMID 37576403, 2023). "The regulation of ARG1 expression in MDSCs by IL-4, HIF-1α, and STAT3 is well established; however, the factors which regulate ARG2 in tumour cells have received less attention to date." (PMID 35962843, 2023). "They act on targets such as IL-6, FOS, STAT3, ERBB2, and EGF, exerting effects on delaying tumor cell resistance and inhibiting tumor cell invasion and metastasis." (PMID 37990309, 2023). "The expression of ARL4C exhibited a significant and positive correlation with immune-related pathways such as TNF-α/NF-κB, INF-γ, INF-α, IL-6/JAK/STAT3, and hypoxia signaling pathways, thereby establishing a connection between ARL4C and tumor immunity." (PMID 38178862, 2023). "Several classical signaling pathways, such as IL-6/signal transducer and activator of transcription (STAT3), HIF1/VEGFA, and PI3K/AKT, have been shown to regulate tumor angiogenesis." (PMID 36720310, 2023). "Here, we show that SC144, a gp130 inhibitor that blocks the IL-6/gp130/STAT3 pathway, induces ICD of tumor cells and polarizes macrophages to M1-phenotype in vitro." (PMID 37553327, 2023). "The GW4064/cisplatin co-treatment remarkably enhances the chemosensitivity of BTC cells in vitro and inhibits the tumor growth in vivo by the upregulation of SHP expression and the downregulation of STAT3 phosphorylation." (PMID 38203175, 2023).
tumor (continued). "STAT3 and hypoxia-inducible factor 1-α (HIF1-α) are important transcription factors involved in M2 polarization in tumor microenvironments." (PMID 37403048, 2023). "By persistently stimulating the signaling pathway of JAK2/STAT3, which is m6A-dependent, upregulation of the ALKBH5-HOXA10 loop enhances EOC tumor development and cisplatin resistance." (PMID 36831377, 2023). "Treatment with EJ inhibits STAT3, which reduces the expression and secretion of the MMP-2 and MMP-9 proteins and exerted an anti-tumor metastasis effect." (PMID 37049904, 2023). "In a recent study, STAT3 activation in GBM cells stimulated by TGF-β and released by M2 TAMs allows GSCs maintenance and self-renewal as a main tumor growth mechanism." (PMID 37190507, 2023). "After 15 days of treatment, E-cadherin, CD68, and CD8 were increased, while vimentin, STAT3, NF-κB, CD163, and CD25 were reduced (as detailed in Table Expression, B and 8 A) in tumours of Balb/c mice when compared to the control group." (PMID 36857852, 2023). "The authors further showed that tumor-derived SHH, through STAT3 signaling, induces PDL1 expression on M2 TAMs to suppress tumor-infiltrating CD8+ T cells, resulting in enhanced tumor progression." (PMID 36674836, 2023). "STAT3 phosphorylation is induced by the cytokine IL-6, one of the main activators that allows STAT3 to bind to vascular endothelial growth factor (VEGF) and consequently promote tumor angiogenesis." (PMID 37511154, 2023). "Inhibition of STAT3 and PI3K/Akt signaling can reverse the suppressive effects on local immunity and reduce tumor size." (PMID 36936946, 2023). "In the present study, Rh4 led to the inactivation of IL-6/STAT3 signaling in LPS-stimulated HCC cells and in the tissues of mouse HCC subcutaneous transplanted tumor, evidenced by reduced IL-6 and p-STAT3 expression." (PMID 37843550, 2023). "Tumor-derived cytokines such as IL-6 and IL-27 have promoted PD-L1+CD8+ T cells development through STAT1/STAT3 signaling." (PMID 37077914, 2023). "Activation of the FGFR2/STAT3 pathway promotes proliferation, invasion, migration, and EMT of tumor cells." (PMID 37750089, 2023). "The Janus kinase/signal transducer and activator of transcription 3 (JAK/STAT3) pathway is crucial in tumorigenesis, exerting regulatory control over tumor initiation, progression and immune responses." (PMID 38455361, 2023). "Hypoxia‐induced formation of the PD‐L1/STAT3 complex promotes expression of GSDMC to induce pyroptosis, followed by tumor necrosis in hypoxic regions, which suppress antitumor immune response from pyroptosis and is critical to tumor proliferation." (PMID 36161280, 2023). "Hnrnpab is a gene encoding for a heterogeneous ribonucleoprotein that is highly expressed in tumor cells, and participates in several cancer-related pathways; such as G2/M checkpoints, DNA repair, and IL6/JAK/STAT3 signaling." (PMID 37583908, 2023). "Activation of these cells produces pro-thrombotic and pro-tumorigenic TF and activates STAT3-mediated IL-6, PAI-1, and MMP-2 production (black upward arrows), and RAS/PI3K/SyK/Ki67/cyclin D1 signaling pathways, leading to tumor growth." (PMID 36751299, 2023). "More recently, it was determined that STAT3 activation increased oncogenic miR-216a, which directly inhibited the tumor suppressor phosphatase and tensin homolog (PTEN), promoting tumor cell growth and resistance." (PMID 37173951, 2023). "In the tumor microenvironment (TME), the IL6/JAK/STAT3 signaling pathway promotes the proliferative, survival, invasive, and metastatic activities of cancer cells, and strongly inhibits the anticancer immune response." (PMID 37651362, 2023). "Talking of feedback mechanisms, CSC encourages TAM to release MGF-E8, which, via STAT3 and sonic hedgehog pathways, induces CSC-led tumor formation and resistance to chemotherapy drugs." (PMID 38035101, 2023).
tumor (continued). "IL-6 induced Janus Kinase (JAK)/signal transducer and activator of transcription 3 (STAT3) activation leads to constitutive activation of STAT3, which correlates with enhanced tumor cell growth and chemotherapy resistance." (PMID 37047012, 2023). "Recent studies have shown that STAT3 signaling can promote angiogenesis by regulating VEGF-A and MMP2 expression, while inhibition of STAT3 activation can inhibit tumor angiogenesis and growth." (PMID 37576403, 2023). "EGFR facilitates tumor cell survival and metastasis by activating signal transduction cascades, including MAPK, AKT and STAT3." (PMID 37924112, 2023). "Signal transducer and activator of transcription 3 (STAT3), an important signaling pathway that mediates immune suppression in the tumor microenvironment, is targeted and suppressed by miR-124, which contributes to the regulation of T-cell functions." (PMID 36768556, 2023). "The following two mechanisms were proposed to explain this; 1) miR-1246 is taken up by ECs in high metastatic tumor EVs, thus inducing ICAM-1 expression via STAT3 activation in ECs." (PMID 37124539, 2023). "In summary, it is clear that overexpression of STAT3 can regulate in various ways the tumor IME, which besides generally promoting tumor progression, is related to poor prognosis, and is consistent with our findings." (PMID 37724127, 2023). "Accordingly, we showed the level of phospho-STAT3 was significantly higher in the late stage of HNSCC, where it was more abundant at the tumor invasive front." (PMID 36446524, 2023). "The combination of ASRPS and the CCD domain of STAT3 can inhibit the phosphorylation of STAT3, thereby reducing the expression of VEGF and inhibiting the formation of tumor blood vessels." (PMID 37691919, 2023). "EGF production by tumor-infiltrating M2 TAMs within the TME can stimulate the NF-κB, STAT3, EGFR, and extracellular signal-regulated kinase signaling axes in tumor cells, promoting their invasive traits." (PMID 38033495, 2023). "Tumour‐derived mediators induce M2 cell polarisation, IL‐6 expression in macrophages and neutrophils through SIRPα/SHP‐1/p38 MAPK/STAT3 signalling." (PMID 36419386, 2023). "Notably, STAT1 is often considered a tumor suppressor because STAT1-deficient mice have been shown to be more prone to spontaneous and chemically induced tumor formation than wild-type mice, so there is an urgent need to find specific target inhibitors of STAT3." (PMID 37173892, 2023). "Upon migration to the tumor microenvironment, M-MDSCs upregulate the activity of CD45 tyrosine phosphatase, which then lead to activation of STAT3." (PMID 36923251, 2023). "STAT3 and STAT5 are activated proteins, which increase tumor cell proliferation, invasion, and survival." (PMID 37298889, 2023). "It activates several downstream signaling pathways, including JAK3/STAT3, Ras/MAPK/ERK, and PI3K/AKT/mTOR, imparting a growth advantage on tumor cells." (PMID 37894456, 2023). "We performed IHC analysis of CD47, p-STAT3, and p-AKT and found that CD47 levels were consistently higher in the tumor tissues than in the normal control tissues." (PMID 36413402, 2023). "In mice bearing STAT3-silenced ovarian SKOV3 tumors, treatment with paclitaxel reduced metastasis, inhibited tumor growth, and increased mice survival." (PMID 38067351, 2023). "High STAT3 activation is found in many GBM tumors, and STAT3 signaling actively participates in GBM tumor formation and progression." (PMID 37242454, 2023). "STAT3 inhibition with AZD1480 or ruxolitinib reduced TAM-mediated MYC upregulation, restraining NBT2 tumor growth in NB-tag and NSG mice." (PMID 38087370, 2023). "While, the immune-related pathways, tumor-related pathways (such as epithelial–mesenchymal transition, IL6 JAK STAT3 signaling, and G2M checkpoint) and inflammation-related pathways were downregulated." (PMID 36445533, 2023).